HSFX4 (heat shock transcription factor family, X-linked member 4)
Gene: Protein-coding gene on chromosome X (149,929,573 to 149,931,287, forward strand). Ensembl gene ENSG00000283463.
Subcellular location: Nucleus
Gene Ontology:
Molecular function: RNA polymerase II cis-regulatory region sequence-specific DNA binding; DNA-binding transcription factor activity; sequence-specific DNA binding
Biological process: regulation of transcription by RNA polymerase II; regulation of DNA-templated transcription
Cellular component: cytosol; nucleus
Homologues: Orthologues: macaque HSFX3 (87% identical), Caenorhabditis elegans hsf-1 (15% identical), Drosophila melanogaster Hsf (14% identical). Paralogues in human: HSFX3 (99% identical), HSFY1 (23% identical), HSFY2 (23% identical), HSFX1 (19% identical), HSFX2 (19% identical), HSF1 (17% identical), HSF5 (17% identical), HSF4 (16% identical), HSF2 (14% identical).